DPP4 (dipeptidyl peptidase 4)
Diseases named in the same sentence as DPP4 in open-access papers (continued):
Sharing a sentence is not in itself a finding about the gene and the disease.
dementia (42 papers, 2017 to 2026). Loss of intellectual abilities interfering with an individual's social and occupational functions. "In matched analyses, the use of SGLT-2 inhibitors and DPP-4 inhibitors was associated with a lower probability of dementia." (PMID 41670429, 2026). "SGLT2 inhibitors were associated with a significantly lower risk of all-cause dementia (HR = 0.74; 95% CI: 0.62-0.87), Alzheimer's disease (HR = 0.62; 95% CI: 0.52-0.74), and vascular dementia (HR = 0.54; 95% CI: 0.49-0.60) compared to DPP-4 inhibitors." (PMID 41777041, 2026). "It is also notable that SGLT2 inhibitor versus DPP4 inhibitor initiation was associated with a lower dementia risk among those with BMI < 30 kg/m2, a subgroup containing some who are at a higher dementia risk in later life." (PMID 41420258, 2025). "The intention-to-treat analysis showed no dementia risk difference between GLP1 receptor agonist and DPP4 inhibitor initiation; however, continuous use of GLP1 receptor agonists versus DPP4 inhibitors was associated with dementia risk reduction." (PMID 41420258, 2025). "Recent population‐based studies have shown encouraging results, with a large cohort study demonstrating reduced risk of dementia in SGLT2 inhibitor users compared to DPP‐4 inhibitor users, particularly after 2 years of treatment." (PMID 40346951, 2025). "DPP-4 inhibitors remain cardiovascularly safe and show intriguing epidemiological associations with reduced dementia and Parkinson’s risk, but dedicated neurological outcome studies are lacking." (PMID 41462689, 2025). "Reduction in all-cause dementia risk with SGLT2 inhibitors versus DPP4 inhibitors was specific to those aged > 70 years (HR [95% CI]: 0.87 [0.77–0.97])." (PMID 41420258, 2025). "Initiation of an SGLT2 inhibitor versus a DPP4 inhibitor was associated with lower dementia risk among people with BMI < 30 kg/m2 (HR [95% CI]: 0.82 [0.70–0.94]) but not among those with BMI ≥ 30 kg/m2 (HR [95% CI]: 0.97 [0.86–1.09]; heterogeneity: p = 0.072)." (PMID 41420258, 2025). "There is limited evidence regarding the effectiveness of GLP-1 agonists compared to DPP-4 inhibitors or sulfonylureas regarding dementia risk in patients with T2DM." (PMID 39429814, 2024). "It found that the use of GLP-1 agonists was associated with a 30% and 23% lower risk of dementia, respectively, compared with sulfonylureas and DPP-4 inhibitors." (PMID 39429814, 2024). "One population-wide cohort study demonstrated a lower risk of dementia in SGLT2 inhibitor-treated elderly T2DM participants in comparison to the DPP4 inhibitor group." (PMID 38255204, 2024). "Our research suggested that GLP-1 agonists were associated with a lower risk of dementia compared to sulfonylureas and DPP-4 inhibitors in older individuals with T2DM." (PMID 39429814, 2024). "GLP-1 agonist initiators had a lower dementia risk compared to sulfonylureas (HR = 0.41, 95% CI: 0.32–0.53) and DPP-4 inhibitors (HR = 0.38, 95% CI: 0.30–0.49)." (PMID 39429814, 2024). "In this emulated trial involving 88,381 older patients with T2DM, we found real-word evidence suggesting that the use of GLP-1 agonists was associated with a reduced risk of developing dementia compared with DPP-4 inhibitors and sulfonylureas." (PMID 39429814, 2024). "This study was the first to compare the effects of GLP-1 agonists, DPP-4 inhibitors, and sulfonylureas on the risk of dementia in older patients with T2DM, using a large sample from nationwide registers and an emulated trial design." (PMID 39429814, 2024). "The effectiveness of GLP-1 agonists and DPP-4 inhibitors in reducing dementia risk in patients with T2DM, compared to each other or sulfonylureas (the most common second-line antihyperglycemic class), remains to be clarified." (PMID 39429814, 2024). "Some observational studies have shown the beneficial effects of DPP-4 inhibitors on the risk of dementia." (PMID 35742986, 2022).
dementia (continued). "Activation of immune cells can release enzymes that can generate soluble forms of receptors, such as sCD40L, sCD163, sCD14, sCD56 (NCAM), sGP130, sRAGE, sCXCL16, and DPP4, all of which have been implicated in dementia and AD." (PMID 36083988, 2022). "An open-cohort study using the Swedish Dementia Registry found that DPP-4 inhibitors were associated with a lower OR for developing dementia and improved MMSE." (PMID 35742986, 2022). "Indeed, Metformin administration was associated with better memory performance in normal cognitive function population, while in AD dementia population, DPP4 inhibitor use was associated with a slowdown of memory decline." (PMID 41480353, 2025). "Moreover, GLP1 receptor agonist versus DPP4 inhibitor initiation showed greater relative reduction in dementia risk among those with < 30 kg/m2 than among those with ≥ 30 kg/m2." (PMID 41420258, 2025). "Finally, a large-scale cohort study in Korea assessed the risk of dementia in adults aged 40–69 years with T2DM who were treated with SGLT2 inhibitors versus DPP-4 inhibitors." (PMID 39728750, 2024). "From the perspective of pathological mechanisms, the study also found the serum dipeptidyl peptidase-4 (DPP4) related to GDM also could significantly alter the risk of dementia in pregnant women (P<0.05)." (PMID 35801085, 2022). "The authors concluded that patients treated with dipeptidyl peptidase-4 (DPP-4) inhibitors presented with the lowest risk of dementia, followed by those treated with metformin and thiazolidinedione, while treatment with insulin was associated with the highest risk." (PMID 35337110, 2022). "However, studies that explored the risk of dementia from the use of the novel oral antidiabetic medication dipeptidyl peptidase 4 inhibitor (DPP-4i) have been limited, especially in Asian populations." (PMID 32121372, 2020). "Besides these RCTs, there is limited evidence from large-scale RCTs or real-world settings on the effectiveness of GLP-1 agonists and DPP-4 inhibitors compared to each other or sulfonylureas, the most commonly used second-line antihyperglycemic class, in dementia risk among patients with T2DM." (PMID 39429814, 2024). "SGLT-2 and DPP-4 inhibitors were associated with a lower risk of dementia, whereas GLP-1 receptor agonists, DPP-4 inhibitors, and SGLT-2 inhibitors were associated with reduced dementia-related mortality." (PMID 41670429, 2026). "Intention-to-treat analyses from rigorous cohort studies with sufficient dementia events showed mixed findings when GLP1 receptor agonists were compared with DPP4 inhibitors." (PMID 41420258, 2025). "We also compared the effects of SGLT2is with those of dipeptidyl peptidase-4 inhibitors (DPP-4i) or glucagon-like peptide-1 receptor agonists (GLP-1RA) on dementia incidence." (PMID 41234238, 2025). "By incorporating this prospective new-user design with active comparators, our study is better positioned to provide more reliable estimates regarding the effects of GLP-1 agonists on dementia relative to DPP-4 inhibitors and sulfonylureas." (PMID 39429814, 2024). "Our findings revealed that GLP-1 agonists were associated with a lower risk of dementia in patients with T2DM, compared to DPP-4 inhibitors or sulfonylureas." (PMID 39429814, 2024). "GLP-1 agonists and DPP-4 inhibitors had a lower dementia risk compared to sulfonylurea initiators (HR for GLP-1 agonists: 0.69, 95% CI: 0.60–0.79; HR for DPP-4 inhibitors: 0.89, 95% CI: 0.82–0.97)." (PMID 39429814, 2024). "Use of metformin, DPP-4 inhibitors, GLP-1 RAs and SGLT2 inhibitors were associated with lower risk of dementia, with a gradual decrease in risk of dementia for each increase in daily defined dose." (PMID 37313236, 2023). "On the other hand, studies that have explored the role of dipeptidyl peptidase 4 inhibitors (DPP-4i) on dementia development in patients with T2D have been limited." (PMID 32121372, 2020).
dementia (continued). "Overall, DPP-4 inhibitors exhibit clear anti-inflammatory/antioxidant actions in preclinical models, but large trials are needed to establish their efficacy for stroke or dementia prevention in humans." (PMID 41462689, 2025). "The relative risk estimates for all-cause dementia with GLP1 receptor agonists versus DPP4 inhibitors did not significantly differ (p = 0.708) between those aged 60–70 (HR [95% CI]: 0.91 [0.81–1.03]) and > 70 years (HR [95% CI]: 0.95 [0.83–1.08])." (PMID 41420258, 2025). "These facts collectively highlight the distinct effects of GLP-1 agonists and reinforce our findings that GLP-1 agonists may indeed provide more substantial protective properties against dementia than DPP-4 inhibitors." (PMID 39429814, 2024). "The relationship between dipeptidyl peptidase-4 inhibitors and dementia was more complex." (PMID 39434474, 2024). "Thus, it is challenging to draw a definitive conclusion about the effectiveness of DPP-4 inhibitors on dementia from our results and the existing trial evidence." (PMID 39429814, 2024). "Nevertheless, our report may provide important insights for the effectiveness and long-term safety of DPP-4 inhibitors in dementia due to tauopathy." (PMID 31126115, 2019). "In fact, DPP4 is a cell surface glycoprotein expressed in different cells such as vascular epithelial cells, immune cells and neurological cells (microglia, neurons, and astrocytes), so its inhibition by DPP4-i may help to protect against dementia." (PMID 41480353, 2025). "The associations of GLP1 receptor agonist versus DPP4 inhibitor initiation with all-cause dementia risk were not statistically significant in those with atherosclerotic cardiovascular disease (HR [95% CI]: 0.89 [0.75–1.05]), and in those with renal insufficiency (HR [95% CI]: 0.87 [0.74–1.03])." (PMID 41420258, 2025). "Moreover, in a Bayesian network meta-analysis, the use of DPP-4 inhibitors was associated with a lower risk of dementia than no treatment with antidiabetic drugs, and DDP-4 inhibitors were the most effective antidiabetic drugs for dementia." (PMID 35742986, 2022). "In contrast, dipeptidyl peptidase-4 (DPP-4) inhibitors, metformin, SGLT2 inhibitors and glucagon-like peptide-1 (GLP1) agonists showed benefit, with metformin barely reaching significance, whereas both SGLT2 inhibitors and GLP1 agonists use displayed a 42% decrease in dementia risk." (PMID 34069618, 2021). "Preclinical and clinical studies suggest the potential role of dipeptidyl peptidase-4 inhibitors (DPP4-i) as therapy for the treatment and prevention of cognitive impairment and dementia." (PMID 41480353, 2025). "A total of 4607 dementia cases developed during follow-up: 278 for the GLP-1 agonist initiators (incidence rate (IR) = 6.7 per 1000 person years), 1849 for DPP-4 inhibitor initiators (IR = 11.8), and 2480 for sulfonylurea initiators (IR = 13.7)." (PMID 39429814, 2024). "A total of 4607 dementia cases developed during follow-up: 278 for the GLP-1 agonist initiators (incidence rate: 6.7 per 1000 person years), 1849 for DPP-4 inhibitor initiators (IR: 11.8), and 2480 for sulfonylurea initiators (IR: 13.7)." (PMID 39429814, 2024).
bullous pemphigoid (41 papers, 2017 to 2026). Bullous pemphigoid (BP) is the most common form of autoimmune bullous dermatosis. "Bullous pemphigoid (BP) is an autoimmune subepidermal blistering disease that predominantly affects elderly individuals and has recently been associated with dipeptidyl peptidase-4 (DPP-4) inhibitor therapy." (PMID 41988607, 2026). "Bullous pemphigoid (BP), the most prevalent autoimmune blistering skin disorder, has been associated with dipeptidyl peptidase-4 inhibitor (DPP4i) treatment in type 2 diabetic patients." (PMID 41373842, 2025). "The association between dipeptidyl peptidase 4 inhibitors (DPP-4 inhibitors) and bullous pemphigoid (BP) has been studied in many countries; however, controversy has arisen from analyzing the related risk factors." (PMID 41471289, 2025). "One of the notable skin disorders induced by DPP-4-is is bullous pemphigoid, named as dipeptidylpeptidase 4 inhibitor-associated bullous pemphigoid (DPP4i-BP) or gliptin-associated bullous pemphigoid (GABP)." (PMID 39065698, 2024). "The following discussion is useful because DPP-4 inhibitors have been associated not only with bullous pemphigoid but also with specific nephropathy." (PMID 38055184, 2024). "The use of dipeptidyl peptidase 4 (DPP4) inhibitors, (also known as gliptins), is associated with an increased risk of bullous pemphigoid (BP), an autoimmune blistering skin disease." (PMID 35958564, 2022). "This study revealed that treatment with dipeptidyl-peptidase 4 inhibitors, especially vildagliptin, is significantly associated with an increased risk of bullous pemphigoid development." (PMID 33573656, 2021). "Recent studies have suggested dipeptidyl-peptidase 4 inhibitors as possible predisposing agents of bullous pemphigoid." (PMID 33573656, 2021). "Third, recent studies suggested that DPP4 inhibitors (especially vildagliptin and linagliptin) are associated with a higher risk of bullous pemphigoid." (PMID 33995274, 2021). "We experienced two cases of dipeptidyl peptidase-4 (DPP-4) inhibitor-associated bullous pemphigoid (BP) showing an unfavorable course despite its discontinuation." (PMID 33088540, 2020). "The use of dipeptidyl peptidase-4 inhibitors (DPP4i) appears to be associated with a small but significantly elevated risk of bullous pemphigoid (BP)." (PMID 33101737, 2020). "Regarding skin lesions, bullous pemphigoid, a rare autoimmune skin disease, was found to be associated with the use of DPP-4 inhibitors in a retrospective analysis of more than 9,000 patients treated in Japan during the years 2009–2017." (PMID 31275246, 2019). "The prevalence of bullous pemphigoid was 0.0859% in total, with a trend toward a higher risk associated with vildagliptin use compared to the other DPP-4 inhibitors." (PMID 31275246, 2019). "Two weeks prior to referral, he developed widespread blisters, initially suspected to represent dipeptidyl peptidase-4 (DPP-4) inhibitor–associated bullous pemphigoid (BP), given the well-established link between DPP-4 inhibitors and autoimmune blistering disorders at that time." (PMID 41562089, 2025). "The objectives of this study are to assess whether the association between DPP-4 inhibitors and bullous pemphigoid in EudraVigilance is statistically significant and to identify the presence of risk factors found in previous studies in a case/exposure group." (PMID 41471289, 2025). "Other pharmacovigilance studies have demonstrated disproportionate reporting for bullous pemphigoid (BP) associated with DPP-4 inhibitors (gliptins), supporting the hypothesis of a potential class effect." (PMID 41471289, 2025). "The author speculated that all DPP-4 inhibitors are selective for the DPP-4 enzyme, and the affinity for the DPP-4 enzyme may contribute to the risk of bullous pemphigoid." (PMID 32938499, 2020).
bullous pemphigoid (continued). "However, there may be an association between DPP-4 inhibitors and the onset of autoimmune diseases, such as bullous pemphigoid and remitting seronegative symmetrical synovitis with pitting edema (RS3PE) syndrome." (PMID 32337291, 2020). "This article describes a case of DPP-4 inhibitor-induced bullous pemphigoid treated with Stapokibart." (PMID 41939756, 2026). "Dipeptidyl peptidase-4 (DPP-4) inhibitors, such as linagliptin, have been implicated in inducing bullous pemphigoid (BP) in elderly diabetic patients." (PMID 41939756, 2026). "The latency period between starting DPP-4 inhibitors and the onset of bullous pemphigoid can be prolonged by several months or even years." (PMID 41471289, 2025). "The median time between the onset of bullous pemphigoid (BP) and the withdrawal of the DPP-4 inhibitor was 36 days." (PMID 41471289, 2025). "The median latency period, defined as the time from the first administration of the DPP-4 inhibitor to the onset of bullous pemphigoid (BP), was 11 months." (PMID 41471289, 2025). "Most studies agree on the long latency period that typically elapses between the initiation of DPP-4 inhibitors and the onset of bullous pemphigoid (BP)." (PMID 41471289, 2025). "recently reported glomerular lesions of TMA-like glomerular microangiopathy as well as bullous pemphigoid after DPP4 inhibitor treatment in type 2 diabetic patients." (PMID 39135967, 2024). "This review article summarizes the current literature on the dermatological side effects of DPP-4 inhibitors, including bullous pemphigoid, severe cutaneous adverse drug reactions, fixed drug eruptions, and other mucocutaneous reactions." (PMID 38523307, 2024). "A meta-analysis conducted in 2018 reported that the incidence of bullous pemphigoid was 3 times higher in patients with type 2 DM using DPP-4 inhibitors." (PMID 38813039, 2023). "We detected bullous pemphigoid in 8% of patients who experienced pruritus and were treated with DPP-4 inhibitors, and it was observed that the patients’ symptoms regressed after changing treatment." (PMID 38813039, 2023). "Incidence rate ratio (IRR) of bullous pemphigoid (BP) with the prescription of DPP4 inhibitors based on MarketScan data." (PMID 36685490, 2022). "Relationship between the emergence of bullous pemphigoid (BP) and the prescription of DPP4 inhibitors (DPP4i) based on FAERS data." (PMID 36685490, 2022). "And the warnings and precautions of DPP-4 inhibitors' latest label in the FDA showed that there have been reports of bullous pemphigoid requiring hospitalization." (PMID 33850463, 2021). "This case suggests that Stapokibart may be an effective treatment for bullous pemphigoid induced by DPP-4 inhibitors." (PMID 41939756, 2026). "While dipeptidyl peptidase-4 (DPP-4) inhibitors are established triggers for bullous pemphigoid (BP), their association with EBA has not been reported." (PMID 41562089, 2025). "Although bullous pemphigoid may be idiopathic, it can be triggered by medications such as antibiotics, NSAIDs, diuretics, or dipeptidyl peptidase-4 (DDP4) inhibitors—often becoming apparent after discontinuation of the offending agent." (PMID 41019039, 2025). "However, some studies have suggested that the combination of metformin and dipeptidyl peptidase 4 (DPP-4) inhibitors could induce bullous pemphigoid." (PMID 38813039, 2023).